AP2S1 (adaptor related protein complex 2 subunit sigma 1)
Description:
Component of the adaptor protein complex 2 (AP-2). Adaptor protein complexes function in protein transport via transport vesicles in different membrane traffic pathways. Adaptor protein complexes are vesicle coat components and appear to be involved in cargo selection and vesicle formation. AP-2 is involved in clathrin-dependent endocytosis in which cargo proteins are incorporated into vesicles surrounded by clathrin (clathrin-coated vesicles, CCVs) which are destined for fusion with the early endosome. The clathrin lattice serves as a mechanical scaffold but is itself unable to bind directly to membrane components. Clathrin-associated adaptor protein (AP) complexes which can bind directly to both the clathrin lattice and to the lipid and protein components of membranes are considered to be the major clathrin adaptors contributing the CCV formation. AP-2 also serves as a cargo receptor to selectively sort the membrane proteins involved in receptor-mediated endocytosis. AP-2 seems to play a role in the recycling of synaptic vesicle membranes from the presynaptic surface. AP-2 recognizes Y-X-X-[FILMV] (Y-X-X-Phi) and [ED]-X-X-X-L- [LI] endocytosis signal motifs within the cytosolic tails of transmembrane cargo molecules. AP-2 may also play a role in maintaining normal post-endocytic trafficking through the ARF6-regulated, non-clathrin pathway. The AP-2 alpha and AP-2 sigma subunits are thought to contribute to the recognition of the [ED]-X-X-X-L-[LI] motif (By similarity). May also play a role in extracellular calcium homeostasis.
Synonyms: AP17; CLAPS2; FBHOk; FBH3; HHC3
Tractability: Antibody: UniProt places it where antibodies can reach, with high confidence; its Gene Ontology location is reachable by antibodies, with high confidence. PROTAC: ubiquitination databases record sites on it; its protein half-life has been measured.
Gene: Protein-coding gene on chromosome 19 (46,838,136 to 46,850,882, reverse strand). Ensembl gene ENSG00000042753.
Subcellular location: Cell membrane; Membrane, coated pit
Pathways (Reactome):
Disease: Dengue Virus Attachment and Entry; Nef Mediated CD4 Down-regulation; Nef Mediated CD8 Down-regulation; Potential therapeutics for SARS
Signal Transduction: Retrograde neurotrophin signalling; WNT5A-dependent internalization of FZD2, FZD5 and ROR2; WNT5A-dependent internalization of FZD4
Developmental Biology: EPH-ephrin mediated repulsion of cells; Recycling pathway of L1
Transport of small molecules: LDL clearance; VLDLR internalisation and degradation
Vesicle-mediated transport: Cargo recognition for clathrin-mediated endocytosis; Clathrin-mediated endocytosis
Immune System: MHC class II antigen presentation
Neuronal System: Trafficking of GluR2-containing AMPA receptors
Gene Ontology:
Molecular function: protein binding; clathrin adaptor activity
Biological process: synaptic vesicle endocytosis; clathrin coat assembly; clathrin-dependent endocytosis; postsynaptic neurotransmitter receptor internalization; regulation of endocytosis; vesicle-mediated transport; intracellular protein transport; protein transport
Cellular component: AP-2 adaptor complex; clathrin-coated endocytic vesicle; clathrin-coated endocytic vesicle membrane; cytoplasmic side of plasma membrane; cytosol; endocytic vesicle membrane; endolysosome membrane; plasma membrane; membrane; membrane coat; postsynapse; presynapse; synapse
Genetic constraint (gnomAD): Loss-of-function variants: 4 observed, 19.14 expected, observed/expected ratio (o/e) 0.21, 90% interval 0.1 to 0.48. The upper end of that interval is the gene's LOEUF score, 0.48, which puts it in group 2 of 6, group 1 being the genes least tolerant of losing a copy. Missense variants: 60 observed, 194.37 expected, observed/expected ratio (o/e) 0.31, 90% interval 0.25 to 0.38. Synonymous variants: 63 observed, 76.44 expected, observed/expected ratio (o/e) 0.82, 90% interval 0.67 to 1.02.
Homologues: Orthologues: mouse Ap2s1 (100% identical), rat Ap2s1 (100% identical), chimpanzee AP2S1 (99% identical), guinea pig AP2S1 (99% identical), pig AP2S1 (99% identical), zebrafish ap2s1 (99% identical), tropical clawed frog ap2s1 (99% identical), Drosophila melanogaster AP-2sigma (96% identical), Caenorhabditis elegans aps-2 (95% identical), macaque AP2S1 (94% identical), dog AP2S1 (73% identical). Paralogues in human: AP1S2 (47% identical), AP1S1 (46% identical), AP1S3 (44% identical), AP3S1 (42% identical), AP4S1 (42% identical), AP3S2 (39% identical).
Diseases named in the same sentence as AP2S1 in open-access papers:
AP2S1 is named in the same sentence as 47 diseases in open-access papers, as found by Europe PMC text mining. Sharing a sentence is not in itself a finding about the gene and the disease. The quoted sentences say what the papers report.
Hypercalcemia (10 papers, 2015 to 2025). An abnormally increased calcium concentration in the blood. "Three of these patients harboured the reported FHH3-causing Arg15His mutation located in exon 2 of AP2S1, and two of these three patients were found to have mild hypercalcaemia." (PMID 29325022, 2018). "Although the detailed mechanism of cognitive impairment due to AP2S1 gene mutation is still unclear, exposure to marked hypercalcemia from infancy or childhood may lead to neurological developmental disability." (PMID 39949382, 2025). "FHH3 patients have heterozygous AP2S1 missense Arg15 mutations (p.Arg15Cys, p.Arg15His or p.Arg15Leu) with hypercalcaemia, which may be marked and symptomatic, and occasional hypophosphataemia and osteomalacia." (PMID 33729479, 2021). "Heterozygous (Ap2s1+/L15) mice were viable, and had marked hypercalcaemia, hypermagnesaemia, hypophosphataemia, and increases in alkaline phosphatase activity and fibroblast growth factor-23." (PMID 33729479, 2021). "Plasma biochemical analysis showed that male and female Ap2s1+/L15 mice had substantial hypercalcaemia with mean calcium concentrations >10 SD above that of respective WT mice." (PMID 33729479, 2021). "Two male Ap2s1L15/L15 mice did survive into adulthood, and both had more severe hypercalcaemia than their male Ap2s1+/L15 litter-mates, thereby also indicating a dosage effect of the mutant Leu15 Ap2s1 allele on plasma calcium concentrations." (PMID 33729479, 2021). "Thus, Ap2s1+/L15 mice had substantial hypercalcaemia with mean plasma calcium concentrations that were >0.5 mmol/l (>20%) above that of WT littermates." (PMID 33729479, 2021). "Before age 8, almost all cases of PTH-dependent hypercalcemia are caused by familial hypocalciuric hypercalcemia (mostly from mutation in CASR, AP2S1, or GNA11) or by neonatal severe primary hyperparathyroidism, both of which have near 100% penetrance for hypercalcemia already in the neonate." (PMID 30065698, 2018). "To ascertain the dose-dependent effects as well as the immediate and later actions of cinacalcet on the hypercalcaemia of FHH3, we administered single oral bolus doses of 0, 30, 60 and 120 mg/kg cinacalcet to Ap2s1+/L15 mice." (PMID 33729479, 2021). "The phenotype of the Trpc1–/– mice is consistent with that of FHH in humans, and the possibility that mutations in the TRPC1 gene may be a cause of hypercalcemia in some patients with FHH who did not have CASR, GNA11, or AP2S1 mutations was therefore explored." (PMID 32213715, 2020).
familial hypocalciuric hypercalcemia (7 papers, 2016 to 2024). Familial hypocalciuric hypercalcemia (FHH) is a generally asymptomatic genetic disorder of phosphocalcic metabolism characterized by lifelong moderate hypercalcemia along with normo- or hypocalciuria and elevated plasma parathyroid hormone (PTH) concentration. "FHPT may also present as non-syndromic PHPT, which includes familial hypocalciuric hypercalcemia (FHH) forms (caused by variants of CASR, GNA11, or AP2S1), neonatal severe hyperparathyroidism, and other forms caused by several genes classified as familial isolated hyperparathyroidism (FIHP)." (PMID 37810884, 2023).
autism (4 papers, 2021 to 2025). Persistent deficits in social interaction and communication and interaction as well as a markedly restricted repertoire of activity and interest as well as repetitive patterns of behavior. "RFX transcription factors bind to a X-box consensus motif, which was found by the authors in some neuronal specific enhancers and/or promoters of autism risk genes (such as AP2S1, KDM6B, ANK2, NONO, and MYT1L)." (PMID 34768579, 2021).
hyperparathyroidism (4 papers, 2017 to 2025). Hyperfunction of the parathyroid glands resulting in the overproduction of parathyroid hormone. "We performed whole exome sequencing in the proband to test for variants in the GNA11 and AP2S1 genes (less common causes of NSHPT) and also analyzed GNPTG as hyperparathyroidism and periosteal changes also occur in I‐cell disease (mucolipidosis Type II)." (PMID 30144375, 2018). "The differential diagnosis consists in the hypocalciuric hypercalcaemia syndrome, types 2 (involving GNA11 gene) and 3 (involving AP2S1 gene); hyperparathyroidism; abnormalities of vitamin D metabolism, involving CYP24A1 and SLC34A1 genes; and reduced GFR." (PMID 28122587, 2017).
Alzheimer disease (3 papers, 2014 to 2022). A progressive, neurodegenerative disease characterized by loss of function and death of nerve cells in several areas of the brain leading to loss of cognitive function such as memory and language. "In recent research, hypoxia-induced miR-210 was shown to target synaptic function genes (GRINA, TMUB1, and AP2S1), plasticity genes (ACTB), Alzheimer’s disease genes (APOE), and genes implicated in MAPK/VEGF and OXPHOS signaling pathways." (PMID 35626359, 2022).
Cognitive impairment (3 papers, 2020 to 2025). Abnormal cognition is characterized by deficits in thinking, reasoning, or remembering. "Mutation analysis of AP2S1 gene for FHH3 should be performed in FHH patients with marked hypermagnesemia, cognitive impairment and low bone mineral density." (PMID 35566721, 2022).
Obesity (2 papers, 2021 to 2024). Accumulation of substantial excess body fat. "Most studies involving AP2S1 were linked to this genetic disease, with one exception linking AP2S1 to obesity, which suggests that its major function is in calcium-sensing pathway." (PMID 34565296, 2021).
parathyroid adenoma (2 papers, 2019 to 2023). "However, in contrast to cases with FHH due to pathogenic variants in CASR, AP2S1, or GNA11, surgery may cure the disease (Case 3) unless hyperplastic glands or other parathyroid adenomas are missed during the first surgery in cases of MGH (Case 2)." (PMID 38130397, 2023).
primary hyperparathyroidism (2 papers, 2021 to 2023). "Features of patients with isolated primary hyperparathyroidism diagnosed with a GCM2 p.Y394S variant, CASR, and AP2S1 mutations." (PMID 38130397, 2023).
colon carcinoma (1 paper, 2023). "Previously, AKF9, a highly antigenic neoantigen originating from the AP2S1 c.258C > G gene mutation in HCT15 colon carcinoma cells, was identified in our laboratory." (PMID 36200687, 2023).
COVID-19 (1 paper, 2021). A disease caused by infection with severe acute respiratory syndrome coronavirus 2. "Another COVID-19-induced change involves the deubiquitination of AP2S1, a subunit of AP2 adapter protein complex for clathrin also included within the Gene Ontology term Viral Process, which may contribute to the viral entrance." (PMID 34198800, 2021).
hypoparathyroidism (1 paper, 2016). Hypoparathyroidism is an endocrine disorder in which the parathyroid glands in the neck do not produce enough parathyroid hormone (PTH). "Moreover, investigations of 10 familial cases and 50 sporadic cases of isolated hypoparathyroidism for coding-region mutations or CNVs affecting AP2S1 did not identify any abnormalities." (PMID 27647839, 2016).
lung carcinoma (1 paper, 2020). "Many new targets of IgGs in lung cancer were non-cell surface proteins, but we noticed that many targets of these IgGs were adaptor proteins, such as the AP-2 complex including AP2A1, AP2A2, AP2B1, AP2S1, and AP2M1." (PMID 32580738, 2020).
pancreatitis (1 paper, 2015). Inflammation of the pancreas. "The Arg15Leu AP2S1 mutation was also associated with recurrent pancreatitis in one FHH3 proband, a finding consistent with FHH1, in which recurrent pancreatitis has occasionally been reported." (PMID 26082470, 2015).
parathyroid tumors (1 paper, 2021). "In molecular genetic analyses of sporadic parathyroid tumors, somatic loss-of-function mutation in the genes encoding GNA11 and AP2S1 have thus far not been described." (PMID 33716975, 2021).
triple-negative breast carcinoma (1 paper, 2022). An invasive breast carcinoma which is negative for expression of estrogen receptor (ER), progesterone receptor (PR), and human epidermal growth factor receptor 2 (HER2). "In addition, AP2S1 was confirmed as a risk factor and was correlated with immune infiltration in triple-negative breast cancer." (PMID 35814377, 2022).
viral infection (1 paper, 2021). "Evidence compiled in miRTarBase indicates that miR-128-1-5p has 3 validated targets—AC1N1, AP2S1, COLGALT1—among the proteins changing after viral infection according to H2V database." (PMID 34198800, 2021).
tumor (13 papers, 2012 to 2025). "Further analysis of the model genes within TCM across pan‐cancer settings revealed that TOMM40, NNT5DC2, NNME, KPNA2, FFOXM1 and AP2S1 were predominantly overexpressed in tumour tissues, while TYRP were highly expressed in normal tissues." (PMID 39054572, 2024). "In total, three potential tumor-specific antigens (AP2S1, P3H4, RAC3) were identified for mRNA vaccine research." (PMID 35814377, 2022). "AP2S1, P3H4 (SC65), SPAG4, PLA2G2F, PTPN6, RAC3, and ETV7 were identified as candidate tumor-associated antigens." (PMID 35814377, 2022). "AP2S1, P3H4, and RAC3 were identified as candidate tumor-specific antigens, and patients with the BCS2 and BCS1A subtypes were identified as candidate populations for mRNA vaccines." (PMID 35814377, 2022). "AP2S1, P3H4, and RAC3 were identified as candidate tumor-specific antigens for BLCA." (PMID 35814377, 2022). "In conclusion, AP2S1, P3H4, and RAC3 were identified as candidate tumor-specific antigens in BLCA, and BCS2 and BCS1A patients may benefit from mRNA vaccine therapy." (PMID 35814377, 2022). "To assess the effect of these changes on the transcriptome, we performed total RNA sequencing on triplicate cultures and five independent tumors derived from CFPAC-1, PANC-1, and BXPC-3 cells, representative of the gradual increase in tumor growth upon AP2 loss, with and without AP2S1 inactivation." (PMID 40050266, 2025).
cancer (12 papers, 2010 to 2025). A tumor composed of atypical neoplastic, often pleomorphic cells that invade other tissues. "As epitopes, we used the HLA-A24-restricted CMVpp65 epitope as a representative viral antigen and the HLA-A24-restricted AKF9 epitope encoded by the mutated AP2S1 gene as a representative cancer antigen." (PMID 40046256, 2025). "When running CBaSe on our pan-cancer dataset, five out of nine genes detected as significant by CBaSe were also detected as significant by SSB-dN/dS (BCL2L12, TERT, AP2S1, KRI1, TMEM214)." (PMID 29855388, 2018).
AP2S1 also shares sentences with these, for which no sentence is quoted: pancreatic cancer (5 papers); bladder cancer (2); breast carcinoma (2); Familial hypocalciuric hypercalcemia type 3 (2); Hypocalciuria (2); myocardial infarction (2); neonatal hyperparathyroidism (2); ovarian carcinoma (2); acute coronary syndrome (1); endocrine diseases (1); epilepsy (1); familial isolated hyperparathyroidism (1); frontotemporal dementia (1); genetic disease (1); head and neck tumors (1); hypophosphatemia (1); intervertebral disc degeneration (1); lymphoma (1); melanoma (1); metabolic disorders (1); mucolipidosis type II (1); multiple endocrine neoplasia type 2 (1); neuroblastoma (1); neurodegenerative disease (1); osteomalacia (1); retinal diseases (1); SARS-CoV Infections (1); schizophrenia (1).